LEP (leptin)
Diseases named in the same sentence as LEP in open-access papers (continued):
Sharing a sentence is not in itself a finding about the gene and the disease.
lipid metabolism disorders (26 papers, 2013 to 2025). "A high-fat diet resulted in glucose and lipid metabolism disorders with higher levels of visceral fat rate, insulin-resistance indices, and leptin." (PMID 34238228, 2021). "Our results suggest that the inulin-supplemented diet alleviates glucose and lipid metabolism disorders by partially restoring leptin related pathways mediated by gut microbiota." (PMID 31026583, 2019). "Overall, our findings showed HFD might influence the process of β-oxidation of fatty acid (Ppara, Acox, and Pgc1a), lipolysis (Atgl, Srebf1, and Hsl), cholesterol removal (Lxra), and appetite regulation (Leptin), leading to lipid metabolism disorder." (PMID 35967777, 2022). "Besides, some studies have shown that glucose and lipid metabolic disorder is related to the abnormal secretion of leptin, which induces oxidative stress in endothelial cells, and further leads to the increase of serum uric acid." (PMID 33514431, 2021). "Lipid metabolism disorders may be related to abnormal levels of lipid metabolism-related regulatory factors, such as adiponectin, leptin, and endolipid." (PMID 33013704, 2020). "Consequently, the synergistic interactions between lipid metabolism disorders and leptin may collectively contribute to the development and progression of AAC in individuals with higher LAP levels." (PMID 40552186, 2025). "Impaired liver leptin-AMPK-ACC signaling pathways were closely related to glucose and lipid metabolism disorders in high fat diet plus low dose of STZ-induced type 2 diabetic rats." (PMID 24455748, 2013). "However, the offspring of the HALEs group had significantly higher serum leptin levels than the offspring of the LALEs and CON groups, which suggested that maternal ALEs diet induced lipid metabolism disorder in offspring." (PMID 38962449, 2024). "We selected oxidative stress and apoptosis-related proteins Fas and cytochrome C, inflammation-related proteins P65 and JNK1/2, lipid metabolism disorder-related proteins SREBP1 and leptin, and insulin resistance-related proteins GSK3β and CYP2E1 for subsequent experimental validation." (PMID 35845577, 2022). "Thus, we hypothesize that COE may elevate leptin expression to activate OB-Rb, which subsequently induces increased phosphorylation of the JAK2/STAT3 pathway involved in hepatic inflammation and lipid metabolism disorder." (PMID 36539694, 2022).
migraine (26 papers, 2012 to 2025). "The reduction in leptin resistance following weight loss may attenuate central neuroinflammation and reduce the likelihood of migraine chronification." (PMID 40426647, 2025). "For example, adipose tissue-derived pro-inflammatory cytokines and neuropeptides like leptin and adiponectin may influence migraine susceptibility and attack frequency." (PMID 40426647, 2025). "In addition, to being implicated in migraine pathogenesis, elevated leptin levels also contribute to the chronification of this illness through systemic inflammation." (PMID 38699683, 2024). "There is also an association between migraines and certain adipokines, such as leptin." (PMID 39452037, 2024). "Increase in body fat, especially in gluteofemoral region, elevates adiponectin and leptin secretion which in turn impair inflammatory processes that could be contributing to migraine risk." (PMID 24250893, 2013). "Subcutaneous fat, often in the gluteo-femoral region in women, appears to increase leptin and adiponectin levels, which may impair insulin sensitivity and modulation of inflammatory processes contributing to migraine risk." (PMID 23181051, 2012). "Researchers have reported that in states where the body has increased leptin levels, these subjects experienced an increase in the number of migraine attacks." (PMID 39452037, 2024). "In a study examining the effects of insulin, glucagon, and leptin in a rat model of migraine, changes in the transmission of trigeminal nociceptive inputs were identified, which provides insight into the dysregulated glucose state associated with migraines." (PMID 36248663, 2022). "Increased fasting levels of neuropeptide Y, leptin and glucagon-like 2 peptide in migraine patients have been suggested to play a role." (PMID 34177788, 2021). "Recently, direct evidence has demonstrated that the role of leptin acted as the key biomarker between CP and migraine in a case–control study." (PMID 33671172, 2021). "Regarding the role of adipokines, leptin is increased in diabetic patients, as well as in patients with migraine and obese individuals." (PMID 34177788, 2021). "Further, in recent years, the relationship between adipocytes released factors, known as adipokines (e.g. adiponectin and leptin) and migraine headache has given more insight into the contribution of adipose tissue in the pathophysiology of migraine." (PMID 31726975, 2019). "Multiple neurotransmitters and hormones, including CGRP, substance P, neuropeptide Y, adiponectin, leptin, orexin-A, interleukin (IL)-1, IL-6, and TNF-α have been implicated in migraine pathogenesis." (PMID 23181051, 2012). "Furthermore, adipose tissue secretes various adipokines, such as leptin and adiponectin, which play important roles in inflammation and migraine." (PMID 40378149, 2025). "Both lipocalin and leptin are elevated between migraine episodes but may be diminished during attacks." (PMID 39600744, 2024). "Peptides such as insulin, glucagon, and leptin, which are involved in blood glucose and appetite regulation, could influence the neurobiology of migraines." (PMID 39452037, 2024). "Leptin is also believed to play a significant role in migraine pathophysiology." (PMID 39452037, 2024). "Likewise, an inflammatory state, induced by leptin and adiponectin secreted by adipose tissue, exists in obesity, and actively contributes to increasing migraine frequency or migraine transformation." (PMID 35370920, 2022). "Additionally, increased leptin level is thought to induce secretion of proinflammatory factors that play a role in migraine (IL-6 and TNF- α) and NO, through NFκβ signaling pathway." (PMID 31726975, 2019). "For instance, Il-1 β and leptin (pro-inflammatory) and oxytocin (anti-inflammatory) exert their effects through specific receptors located either at the terminal C-fibers (neuropathic pain) or the trigeminal ganglion (migraine)." (PMID 31554241, 2019).
migraine (continued). "However, the results of the researches concerning the association between leptin levels and migraine have not been conclusive yet." (PMID 31726975, 2019). "It has been suggested that insulin, glucagon, and leptin may alter the transmission of nociceptive inputs from the trigeminal nerve to higher brain regions, implying that adipokine signaling could influence specific neural networks involved in the development of migraines." (PMID 39452037, 2024). "Furthermore, elevated leptin level is thought to induce the secretion of pro-inflammatory factors (IL-6 and TNF- α) and NO that play a role in migraine through the NF-κβ signaling pathway." (PMID 38243194, 2024). "Recent studies have revealed numerous associations between CSD and other pathological and physiological processes, including migraines, glucose dysregulation, traumatic brain injury (TBI), cerebrovascular accidents (CVA), various biomarkers, and oligemia, orexin, and leptin." (PMID 39452037, 2024). "Leptin levels are also increased in correlation with pro-inflammatory cytokines IL-6 and TNF-a, which have also been found to be elevated in people with migraine." (PMID 32762643, 2020). "Moreover, leptin might be involved in the pathogenesis of migraine with and without aura." (PMID 34177788, 2021).
mood disorder (26 papers, 2012 to 2026). A cognitive disorder a disturbance in which the person's mood is hypothesized to be the main underlying feature. "The effect of leptin on cocaine-seeking may be related to its inhibitory effect on the brain reward system and the known effect of leptin mutations in mood disorders." (PMID 35316955, 2022). "Both GDNF and leptin exert neurotrophin-like actions in the hippocampus, and disturbances in the availability and function of either effector has been implicated in the development of mood disorders." (PMID 33013310, 2020). "Recently, growing experimental results indicate that leptin also plays a significant regulatory role in the central nervous system (CNS) and is associated with several pathological and physiological mechanisms of neurological diseases, including neurodegenerative diseases and mood disorders." (PMID 31130833, 2019). "Overall, leptin was found to be another common mediator regulating mood disorder and metabolic homeostasis." (PMID 36077028, 2022). "The distribution of leptin signaling in the brain is related to emotional and cognitional processes, which has sparked an increased interest in the role of leptin in mood disorders." (PMID 35911226, 2022). "In this article, we mainly discuss the role of leptin in mood disorder and neurodegenerative diseases and try to interpret the potential mechanisms." (PMID 31130833, 2019). "Leptin is involved in neuroimmune interactions that link obesity, inflammation, and mood disorders, as it stimulates the release of proinflammatory cytokines such as IL-6, TNF-α, and IFN-γ, which are well-established activators of IDO1, thereby increasing the degradation of Trp through the KP." (PMID 41516008, 2025). "In addition, studies in humans have provided evidence about the role of leptin in mood disorders." (PMID 36077028, 2022). "Moreover, the relationship between leptin and mood disorders was investigated." (PMID 24906408, 2014).
Sleep apnea (26 papers, 2008 to 2024). An intermittent cessation of airflow at the mouth and nose during sleep is known as sleep apnea. "Furthermore, increased leptin levels were positively associated with the severity of sleep apnea measured by AHI and oxygen saturation below 90% time." (PMID 29675134, 2018). "Thus, both relative leptin deficiency and leptin resistance may be associated with sleep-disordered breathing in humans." (PMID 29675134, 2018). "Among them, adiponectin, an adipokine recognized to counteract the effect of leptin, is decreased under IH and in sleep apnea patients." (PMID 37964925, 2023). "In subsequent work, our group have shown that DIO mice develop sleep disordered breathing, despite high circulating leptin levels and leptin resistance." (PMID 31766589, 2019). "The current review summarizes recent data on a possible link between leptin and oxidative stress in the pathogenesis of sleep breathing disorders." (PMID 29675134, 2018). "Leptin resistant New Zealand Obese mice exhibit inspiratory flow limitation, suggestive of sleep disordered breathing." (PMID 30127766, 2018). "Leptin was significantly increased in sleep apneas compared to levels in both BMI-matched obese and normal weight subjects and a reduction of serum leptin levels was observed after weeks or months of continuous positive airway pressure (CPAP) treatment." (PMID 24466027, 2014). "Treatment of sleep-disordered breathing with continuous positive airway pressure led to a significant decrease in leptin levels." (PMID 18762497, 2008). "Interestingly, leptin and ischemia-reperfusion injury (i.e., typical of sleep apnea) have been shown to regulate the expression of matrix metalloproteinase-9 (MMP-9)." (PMID 36380123, 2023). "Taken together, this evidence indicates that leptin acts in the CB, activating LepRb in the glomus cells to increase ventilation in response to hypoxia and during sleep, which could be a possible protective mechanism against sleep-disordered breathing." (PMID 32698380, 2020). "In RH the adipokine leptin is associated with lack of BP control primarily mediated by leptin sympathoexitatory effects and renin–angiotensin–aldosterone activation that are also seen in sleep apnea." (PMID 29867728, 2018).
hyperuricemia (25 papers, 2004 to 2025). An abnormally high level of uric acid. "For instance, hyperuricemia is associated with low adiponectin and high leptin levels." (PMID 39836643, 2025). "Bedir A and Fruehwald-Schultes B found that serum uric acid concentration was independently associated with serum leptin concentration, which suggested that leptin may be a pathogenic factor of hyperuricemia in obese patients." (PMID 39388423, 2024). "Firstly, leptin was found to be a causative factor for hyperuricemia in obese patients." (PMID 37274813, 2023). "However, there have been no studies in children and adolescents to demonstrate an association between leptin and hyperuricemia." (PMID 37274813, 2023). "Some studies showed that leptin could be a pathogenic factor responsible for hyperuricemia in obese patients." (PMID 29785038, 2018). "There is some evidence that the rise in uric acid may be the consequence of elevated leptin levels because loss of leptin receptor signaling also engenders hyperuricemia." (PMID 23369448, 2012). "In addition to IR, leptin was found to be a causative factor for hyperuricemia in obese patients and was hypothesized to be an association between the two." (PMID 37274813, 2023). "The study aimed to assess the relationship between metabolic parameters, inflammation, UA, ghrelin, and leptin in patients with urolithiasis, hyperuricemia and MetS." (PMID 36830821, 2023). "Despite some limitations, this study revealed significant correlations between ghrelin and leptin, between these hormones and IL-6, and between leptin and UA in patients with hyperuricemia, urolithiasis and MetS." (PMID 36830821, 2023). "Leptin concentrations were positively correlated with UA in premenopausal females and elevated in females with hyperuricemia." (PMID 35268067, 2022). "Taken together these data suggest a mechanism by which diminished tumor cell XOR in conjunction with hyperuricemia and elevated leptin promote cancer cell proliferation, migration, and survival." (PMID 23369448, 2012). "Based on these studies, it is reasonable to deduce that the age-based DII-hyperuricemia relationship might be influenced by leptin levels." (PMID 37810924, 2023). "Increased leptin secretion, which is one of the cytokines produced by adipose tissue, may also result in hyperuricemia by decreasing renal uric acid excretion." (PMID 36904083, 2023). "As hyperuricemia is closely related to the serum leptin level, the negative correlation between leptin and GH may indirectly support the relationship between low peak GH and hyperuricemia." (PMID 29785038, 2018).
Hypoglycemia (25 papers, 2010 to 2025). A decreased concentration of glucose in the blood. "Compared with insulin administration, treatment with leptin is associated with a lower risk of hypoglycemia, directly inhibits fat synthesis and is an effective treatment for ketoacidosis, a life-threatening complication of T1DM." (PMID 40429740, 2025). "This recombinant hormone has a high cost, difficult accessibility, and side effects, including hypoglycemia, weight loss, and the possible appearance of neutralizing antibodies to leptin." (PMID 38260129, 2023). "Similar results were observed in this study; our data revealed that endotoxins cause significant systemic inflammation (upregulation of TNF-α, IL-6, and leptin in plasma) and metabolic alterations (body weight loss and severe hypoglycemia) in obese mice." (PMID 35056093, 2021). "In general, males and females equally responded to the corresponding metabolic situation: fasting caused decrease of body and liver weights, loss of fat stores, hypoglycemia, decrease of leptin and increase of FGF21 and adiponectin blood levels." (PMID 31783664, 2019). "The GTT was performed after fasting for 2 h, based on previous reports, because mice with IDDM treated with leptin develop severe hypoglycemia after prolonged fasting." (PMID 40429740, 2025). "It included lowering insulin doses in alignment with caloric restrictions to prevent hypoglycaemia or treating those with leptin resistance with medications to boost anorexigenic effects while they worked towards developing self-maintenance strategies." (PMID 36232191, 2022). "Despite high circulating levels of insulin and leptin in the present animal model of hypoglycaemia, the animals have increased food consumption, presumably driven mainly by the hypoglycaemia." (PMID 28421113, 2017). "Leptin rose at 18 h and 24 h, after hypoglycemia was established." (PMID 36548717, 2022). "Leptin (LEP) is a hormone, primarily derived from adipose tissue, with anti-diabetic features that regulates numerous physiological processes and behaviors, including appetite, body weight, neuroendocrine functions, and hypoglycemia." (PMID 32405365, 2020). "Taking this into account, we investigated whether leptin treatment reduced the hypoglycemia observed in endotoxemia." (PMID 30618812, 2018). "Reversely, naturally occurring hypoglycaemia induced by fasting is typically accompanied by a decrease in plasma insulin and leptin levels and increased neuronal GLUT3 levels, presumably to compensate for restricted supply of glucose from peripheral circulation." (PMID 28421113, 2017). "The hypoglycaemia-induced hyperphagia despite hyperinsulinaemia has been shown before, indicating that, with regard to control of appetite, the glucose availability dominates over insulin and leptin signalling, at least initially in the present model." (PMID 28421113, 2017). "Furthermore, the systemic spike of plasma leptin injections can lead to hypoglycemia, and other complications." (PMID 27055280, 2016). "Further research is needed to examine the physiological mechanisms underlying the relationship between fasting and balance including the role of energy regulating hormones (insulin, leptin, adiponectin, ghrelin) as well as the resulting metabolic and biochemical changes (e.g., hypoglycemia)." (PMID 20388217, 2010). "Hypoglycemia is the most serious complication of insulin therapy; therefore, adjunctive leptin treatment could reduce the severity of these episodes; indeed, the combination of insulin and leptin in T1DM mice was shown to improve glycemic stability." (PMID 36674935, 2023). "The application of orexin, insulin, PACAP, CRF, leptin, CART, CCK, and hypoglycemia (2 mM glucose) to the brain resulted in sympathetic nerve excitation." (PMID 30832213, 2019). "Decreased leptin levels by fasting trigger lipolysis in WAT via activation of HPA-axis, leading to glucose-counterregulatory actions in response to starvation-induced hypoglycemia." (PMID 33071988, 2020).
Hypoglycemia (continued). "A similar analysis was performed for HY TME in SGH that exhibit a loss of body mass during the late clinical phase of disease and these animals have a different profile that includes hypersecretion of glucagon, increased fasted ß-ketones, fasted hypoglycemia, and suppressed, non-fasted leptin." (PMID 22174765, 2011).